GAS2L3 (growth arrest specific 2 like 3)
Description:
Cytoskeletal linker protein. May promote and stabilize the formation of the actin and microtubule network.
Synonyms: G2L3
Tractability: PROTAC: ubiquitination databases record sites on it.
Gene: Protein-coding gene on chromosome 12 (100,573,681 to 100,628,288, forward strand). Ensembl gene ENSG00000139354.
Subcellular location: Cytoplasm; Cytoplasm, cytoskeleton
Gene Ontology:
Molecular function: actin binding; microtubule binding; protein binding; actin filament binding
Biological process: actin cytoskeleton organization; microtubule cytoskeleton organization; actin crosslink formation
Cellular component: actin cytoskeleton; cytoplasm; microtubule cytoskeleton; cytoskeleton
Genetic constraint (gnomAD): Loss-of-function variants: 9 observed, 13.87 expected, observed/expected ratio (o/e) 0.65, 90% interval 0.39 to 1.13. The upper end of that interval is the gene's LOEUF score, 1.13, which puts it in group 4 of 6, group 1 being the genes least tolerant of losing a copy. Missense variants: 590 observed, 640.11 expected, observed/expected ratio (o/e) 0.92, 90% interval 0.86 to 0.99. Synonymous variants: 218 observed, 238.81 expected, observed/expected ratio (o/e) 0.91, 90% interval 0.82 to 1.02.
Homologues: Orthologues: chimpanzee GAS2L3 (99% identical), macaque GAS2L3 (96% identical), pig GAS2L3 (80% identical), rabbit GAS2L3 (80% identical), mouse Gas2l3 (76% identical), rat Gas2l3 (74% identical), guinea pig GAS2L3 (69% identical), dog GAS2L3 (66% identical), tropical clawed frog gas2l3 (48% identical), zebrafish gas2l3 (34% identical). Paralogues in human: PLEC (17% identical), DST (16% identical), SPTB (16% identical), SPTBN1 (16% identical), MACF1 (16% identical), SPTBN2 (16% identical), SYNE1 (16% identical), FLNB (15% identical), SPTBN4 (15% identical), SYNE2 (15% identical), FLNC (15% identical), FLNA (14% identical), and 24 more.
Diseases named in the same sentence as GAS2L3 in open-access papers:
GAS2L3 is named in the same sentence as 11 diseases in open-access papers, as found by Europe PMC text mining. Sharing a sentence is not in itself a finding about the gene and the disease. The quoted sentences say what the papers report.
glioma (7 papers, 2021 to 2024). A benign or malignant brain and spinal cord tumor that arises from glial cells (astrocytes, oligodendrocytes, ependymal cells). "We also analyzed the mutation status of GAS2, GAS2L1, GAS2L2, and GAS2L3 in the glioma samples of TCGA‐LGG/GBM or CGGA‐WEseq_286 project, respectively." (PMID 33713047, 2021). "GAS2L3 gene is capable of influencing the proliferation and migration ability of glioma cells and may be linked to a series of immune cell infiltration or cell division‐associated events in the etiology and biology of glioma." (PMID 33713047, 2021). "Finally, we analyzed the association between GAS2L3 gene expression and the proliferation or migration processes of two human glioma cell lines (N9, N33)." (PMID 33713047, 2021). "Moreover, the GAS2L3 gene can affect the proliferation and migration ability of glioma cells and may be associated with a series of immune cell infiltration or cell division‐associated events in the etiology and biology of glioma." (PMID 33713047, 2021). "Therefore, GAS2L3 expression is associated with the migration ability of glioma cells." (PMID 33713047, 2021). "Compared with GAS2, GAS2L1, and GAS2L2, there is a stronger correlation between GAS2L3 gene expression and glioma prognosis." (PMID 33713047, 2021). "These suggested the potential functional links of GAS2L3 expression and the immune cell infiltration for the brain lower grade glioma tissues." (PMID 33713047, 2021). "After analyzing the datasets of Oncomine, TCGA, and GTEx databases, we observed a higher expression level of GAS2L3 in the glioma tissues than the normal controls." (PMID 33713047, 2021). "In summary, compared with GAS2, GAS2L1, and GAS2L2, there is a stronger correlation between GAS2L3 gene expression and glioma prognosis." (PMID 33713047, 2021). "Herein, we first comprehensively explored the potential correlation between growth‐arrest‐specific two family genes (GAS2, GAS2L1, GAS2L2, GAS2L3) and gliomas by bioinformatics analysis and cellular experiments." (PMID 33713047, 2021). "Very recently, we reported that the high expression of GAS2L3 is closely related to an enhanced proliferation and migration of glioma cells." (PMID 34238242, 2021). "The results showed that, compared with the vector group, the down‐regulation of the GAS2L3 gene in the sh‐GAS2L3‐#1 and sh‐GAS2L3‐#2 groups led to a reduced migration trend of glioma cells, especially at the point of 48 h (p < 0.05)." (PMID 33713047, 2021). "This study first analyzed the potential role of GAS2 family genes, especially GAS2L3, in the clinical prognosis and possible functional mechanisms of glioma, which gives a novel insight into the relationship between GAS2L3 and LGG." (PMID 33713047, 2021). "Compared with other GAS2 family members, there was a strong correlation between the GAS2L3 gene expression and the prognosis of glioma patients." (PMID 33713047, 2021). "Knockdown of Gas2l3 expression in zebrafish embryos caused abnormal ventricle formation and brain dysmorphogenesis The expression of another DCA/CDCA regulated gene, IKBIP, showed positive correlation with glioma grade." (PMID 37259326, 2023). "CGGA‐based data analysis indicated that high expression of GAS2L3 is associated with poor clinical prognosis of the primary glioma cases, but not the recurrent glioma cases." (PMID 33713047, 2021). "DNA hypomethylation of GAS2L3 may contribute to the high expression level of GAS2L3 and the poor clinical prognosis of glioma." (PMID 33713047, 2021). "Additionally, our cellular experiment data suggested that a highly expressed GAS2L3 gene contributes to the enhanced proliferation and migration of glioma cells." (PMID 33713047, 2021). "DNA hypomethylation of GAS2L3 may contribute to the high expression level of GAS2L3 and the poor clinical prognosis of glioma cases." (PMID 33713047, 2021).
glioma (continued). "Besides, we performed a prognostic analysis on the three datasets (array_301, seq_325, seq_693) of CGGA and observed a correlation between the high expression of GAS2L3 and poor clinical prognosis of primary glioma cases (all p < 0.0001)." (PMID 33713047, 2021). "In addition, GAS2L3 expression was positively correlated with WHO gradings of glioma cases within the CGGA database." (PMID 33713047, 2021). "Moreover, we performed cellular experiments to study the relationship between the expression of the GAS2L3 gene and the in vitro proliferation and migration ability of glioma cells." (PMID 33713047, 2021). "Functional enrichment analysis of GAS2L3‐correlated genes and interaction partners further indicated that GAS2L3 might take part in the occurrence of glioma by influencing a series of biological behaviors, such as cell division, cytoskeleton binding, and cell adhesion." (PMID 33713047, 2021). "Then, we conducted a series of correlation analyses on the glioma cases within the TCGA and CGGA databases and observed a strong correlation between GAS2L3 and these common genes." (PMID 33713047, 2021). "Apart from GAS2L3, we did not observe the strong evidence supporting the significant expression difference of the GAS2, GAS2L1, and GAS2L2 genes between glioma cases and negative controls." (PMID 33713047, 2021).
Breast invasive carcinoma (1 paper, 2021). "For instance, compared with normal tissues of TCGA‐BRCA (Breast invasive carcinoma), we observed a lower expression level of GAS2 and GAS2L2 genes (p < 0.001), but a high expression level of GAS2L3 (p < 0.001) in the tumor tissues." (PMID 33713047, 2021).
esophageal carcinoma (1 paper, 2021). A primary or metastatic malignant neoplasm involving the esophagus. "Additionally, the GAS2L3 gene was highly expressed in other tumors, such as cholangio carcinoma (CHOL), esophageal carcinoma (ESCA), kidney renal clear cell carcinoma (KIRC), stomach adenocarcinoma (STAD), and uterine corpus endometrial carcinoma (UCEC), compared with adjacent controls (p < 0.001)." (PMID 33713047, 2021).
gastric cancer (1 paper, 2021). A primary or metastatic malignant neoplasm involving the stomach. "The treatment of highly cytotoxic alpha‐emitter‐immunoconjugates can result in the downregulation of GAS2L3 expression in gastric cancer HSC45‐M2 cells." (PMID 33713047, 2021).
glioblastoma multiforme (1 paper, 2021). "Moreover, our pooled analysis of eight datasets of Oncomine showed a higher expression level of the GAS2L3 gene in glioblastoma tissues than the normal tissues (p = 0.019)." (PMID 33713047, 2021). "Hence, DNA methylation and immune infiltration are more likely to contribute to the molecular mechanism of GAS2L3 involved in the pathogenesis of LGG, but not glioblastoma multiforme." (PMID 33713047, 2021).
liver cancer (1 paper, 2021). An epithelial or non-epithelial malignant neoplasm that arises from the liver. "The function of GAS2L3 is still unknown, and GAS2L3 may be involved in mediating the absorption and clearance of prostaglandins, but its function in liver cancer has not been reported." (PMID 33402113, 2021).
tumor (7 papers, 2016 to 2025). "For the downregulated genes, Id1, Tor4a, Fam83d, Chst12, Fhod1, Sapcd2, and Gas2l3 are known as proliferative and metastatic oncogenes contributing to tumor progression." (PMID 40231790, 2025). "Additionally, more cell, animal and clinical sample‐based investigations are needed to further explore the potential role or clinical benefits of GAS2L1, GAS2L2 and GAS2L3 in the aetiology and pathogenesis of relevant diseases, such as tumours." (PMID 33103301, 2021). "In this study, we found that GAS2L1 and GAS2L3 were distinctly upregulated in HCC specimens compared to non-tumor specimens." (PMID 38858234, 2024).
cancer (5 papers, 2020 to 2024). A tumor composed of atypical neoplastic, often pleomorphic cells that invade other tissues. "Then, we explored the TTK, C16orf54, PPAT, CD3EAP, SLCO2A1, ACAT1, and GAS2L3 genes in the CBioPortal for cancer genomics." (PMID 33402113, 2021). "Pan-cancer assays indicated that GAS2L1 and GAS2L3 were highly expressed in most cancers." (PMID 38858234, 2024). "MAX (a MYC interacting partner), miR-150, miR-133a, FOLR1, E2F NCAM1, GAS2L3 and ATF5 are the most significantly associated upstream regulators, while cancer, neurogenesis, metastasis and cellular development are the most important biological functions affected in this subgroup." (PMID 32591022, 2020). "These suggested that the high expression of GAS2L3 is not specific to one cancer type." (PMID 33713047, 2021).
GAS2L3 also shares sentences with these, for which no sentence is quoted: stomach adenocarcinoma (1 paper); thyroid cancer (1); uterine corpus endometrial carcinoma (1).